LTF (lactotransferrin)
Diseases named in the same sentence as LTF in open-access papers (continued):
Sharing a sentence is not in itself a finding about the gene and the disease.
tumor (78 papers, 2008 to 2026). "Conversely, downregulation of genes, like LGALS4 and LTF, is linked to tumor progression and metastasis." (PMID 40802546, 2025). "The aim of this study was to examine the possible association between CDKN2A, MDM2, E2F2 and LTF mRNA expression in the OSCC tumour and margin samples and influence on clinical variables in the Caucasian Polish population." (PMID 36551770, 2022). "SPLUNC1, UBAP1, BRD7, NAG7, NOR1, NGX6 and LTF genes were found to be tumor suppressor/susceptibility genes in different stages of NPC." (PMID 19949542, 2009). "Moreover, we depleted LTF in GBM cells, and cellular and animal results indicated that loss of LTF significantly inhibited tumor progression." (PMID 40960773, 2025). "Importantly, this down-regulation is concurrently associated with increased sensitivity of RCC tumor cells to mTOR inhibitors, suggesting that lactotransferrin may serve as a predictive biomarker for therapeutic response." (PMID 41566198, 2026). "In the cell clusters collected from the lung (C2, C3, C12, C13, and C19), shared TFs among malignant and precancerous cells included LTF, IRX5, SIX1, and RUNX1, associated with tumor invasion and metastasis." (PMID 39872221, 2025). "LTF is involved in many biological functions such as anti-inflammatory, anti-oxidative, and anti-tumor processes." (PMID 40988744, 2025). "Molecules such as fractalkine, lactotransferrin, and prostaglandin E2 are released by apoptotic cells to recruit macrophages and can also act on tumor cells to promote survival and proliferation." (PMID 40730678, 2025). "As an active iron‐binding protein from the transferrin family, LTF exhibits tumor suppressive effects in various cancer types." (PMID 37545464, 2024). "To determine the contribution of LTF in the tumor radioresistance in vivo, we administrated cholesterol-modified si-LTF or its control into the xenograft of H226R and H1703R cells every 3 days during tumor growth." (PMID 37056929, 2023). "We also found by IHC that LTF expression was abnormally elevated in immune cells in the CRC tumor microenvironment." (PMID 37313408, 2023). "Since E6, E7, MAP7 and LTF are also related to tumor cell apoptosis, we used flow cytometry to further evaluate SiHa cell apoptosis after treatment with CLD." (PMID 37344615, 2023). "Lactotransferrin was differentially expressed between solid and other tumor types, while mucin-5B showed significant difference between all the three tumor groups." (PMID 37069213, 2023). "Here, we determined that patients with the MIF SNP rs755622 have an altered tumor microenvironment characterized by increased lymphocyte infiltration and enhanced lactotransferrin (LTF) expression." (PMID 37252795, 2023). "In summary, we have not demonstrated that a change in expression profiles of CDKN2A, MDM2, E2F2 and LTF genes in tumour and margin tissues has a significant impact on the pathogenesis of OSCC." (PMID 36551770, 2022). "We found no statistically significant dissimilarities in the expression level of LTF genes in the tumour and margin specimens." (PMID 36360322, 2022). "The results indicated that the expression of LTF in tumor tissues was significantly lower than that in adjacent tissues." (PMID 34266418, 2021). "Differential analysis of 33 tumor types showed that LTF was differentially expressed in 20 tumor types." (PMID 34868909, 2021). "The pan-cancer analysis confirmed the low expression of LTF in most tumors, including PRAD, and confirmed that LTF was a tumor suppressor gene." (PMID 34868909, 2021). "DNAH5, LTF, and Ezrin were significantly increased in tumor tissues (p < 0.05), and WNT7A displayed a slight increase (p = 0.0669)." (PMID 35178403, 2021). "It shows that the high expression of LTF makes the tumor remain in a state of continuous remission to a certain extent; that is, the symptoms are improved and the effect of chemotherapy is good." (PMID 34868909, 2021).
tumor (continued). "The results showed that the expression of LTF in tumor tissues was significantly lower than that in normal tissues." (PMID 34266418, 2021). "The tumor-promoting role of LTF as demonstrated in this study, is supported by a recent report that 100 μg mL−1 LTF promotes invasiveness in triple-negative breast cancer." (PMID 32669559, 2020). "Next, MethylMix-PA identified hyper-methylation across the promoter region of LTF, a likely tumor suppressor which is produced by neutrophils to regulate growth and differentiation." (PMID 31356589, 2019). "The mRNA expressions of TGFβ1, MMP8 (matrix metalloproteinase 8), and LTF (lactoferrin), which all show tumor suppressing ability, were significantly increased in Rheb1Δ/Δ GFP+ cells compared with the control." (PMID 27071307, 2016). "For instance, LTF, one iron-binding member of the transferrin family, has been demonstrated to regulate the tumor growth via mediating the transition from the G1 to S phase of cell cycle." (PMID 27034707, 2016). "The expression of miR-214 is upregulated in NPC samples, especially in metastasis-prone NPC tumor tissues, while the lactotransferrin (LTF) expression level is negatively correlated with that of miR-214." (PMID 25427638, 2015). "Locus 3p21.31 contains a number of tumour-suppressor genes (LIMD1, LTF, CDC25A, SCOTIN, RASSF1a, and CACNA2D2) of which alterations to LTF and RASSF1A were associated with significantly worse outcome in oral cavity disease in an Indian cohort." (PMID 24364026, 2013). "Some of the tumour suppressor genes identified in our study included Lactotransferrin (LTF), MFNG and SOSTDC1." (PMID 21092330, 2010). "To further elucidate this mechanism, we hypothesized that the anti-tumor effects of LTFe are primarily mediated through the upregulation of LTF expression." (PMID 40082405, 2025). "In addition to the iron delivery capacity, LTF can function as either an oncogene or a tumor suppressor." (PMID 40960773, 2025). "Interestingly, LTF has been described to act as a tumour suppressor in several models of solid tumours including breast and nasopharyngeal carcinomas." (PMID 38316788, 2024). "The results showed that the knockdown of key genes (HMOX1, STEAP3, and LTF) combined with TMZ treatment significantly decreased both tumor volume and tumor weight compared to the group treated with TMZ alone, indicating an effective restoration of sensitivity to TMZ therapy." (PMID 37545464, 2024). "LTF could act as a tumor suppressor by inhibiting the AKT signaling pathway or by releasing BAX27,45." (PMID 37344615, 2023). "In addition, by mimicking survival rate analysis widely used in tumor biology, we found that LTF and SOD2 were prognostic factors of gestational age, with higher levels denoting shorter gestational age." (PMID 36966172, 2023). "In addition, NEDD4L is also found to protect tumor cells from undergoing ferroptosis by promoting the ubiquitin-mediated degradation of lactotransferrin (LTF)." (PMID 38174069, 2023). "Our study found seven downstream factors that may be associated with chemoresistance, LTF, SOD2, STAT1, CDKN2A, CD81, RAC1, and NDRG1 and five factors that may be associated with tumor development, CCN1, DCTN3, MUC1, H1-5, and SLC1A5." (PMID 35421932, 2022). "LTF has been considered as a tumor suppressor in multiple cancers." (PMID 35096061, 2022). "LTF protein downregulation was observed both in tumour tissues and in serum." (PMID 36360322, 2022). "The ssGSEA results further verified that the LTF expression level may influence the immune status of the tumor microenvironment." (PMID 34266418, 2021). "The experimental results verify our above analysis; that is, overexpression of LTF in PRAD cells can affect the expression of STAT3 through JAK/STAT pathway to reduce tumor-derived GM-CSF secretion and then interfere with the local immunosuppressive function of MDSCs." (PMID 34868909, 2021).
tumor (continued). "In the case of lactotransferrin, a glycoprotein that also can link to iron, several biological activities were also described: iron homeostasis, anti-microbial and immunomodulatory effects and anti-tumor activity." (PMID 34356534, 2021). "The downregulation of LTF is accompanied by tumor growth, invasion and metastasis." (PMID 34266418, 2021). "The results show that overexpression of LTF may reduce the secretion of GM-CSF by tumor cells through JAK/STAT3 pathway to regulate the tumor immune microenvironment and inhibit tumor cell proliferation and migration." (PMID 34868909, 2021). "Similarly, our analysis found decreased expression of genes that have been supported by NPC studies such as LTF, which has been shown to have an anti-tumor and anti-metastasis effects in NPC through suppressing Akt." (PMID 34648530, 2021). "Thus, LTF has the function of regulating tumor immune microenvironment and inhibiting tumor cell proliferation and migration." (PMID 34868909, 2021). "METTL7A and LTF are reported to act as tumor suppressor genes." (PMID 34123594, 2021). "The lactoferrin (LTF) gene, located at 3p21.3, acts as a tumor suppressor gene in diverse tumors." (PMID 33585219, 2020). "The consistent upregulation of LTF may suggest an inflamed tumor microenvironment, indicating the possibility of microbial infections and/or potentially altered iron metabolism that may contribute to subsequent resistance to systemic topotecan administration." (PMID 31195594, 2019). "Precancerous clusters showed enrichment in tumor progression-related regulons, including transcription factors (TFs) linked to tumor proliferation and cell cycle progression (STAT1, BCL6, ETV5) and potential tumor suppressors (ELF5, LTF, RXRG, CEBPD), as well as EMT-related regulons." (PMID 39872221, 2025). "Moreover, FCGR2B, HLA-DQA2, and LTF are involved in tumor or organ transplantation." (PMID 35755170, 2022). "LTF may act as a tumor suppressor, downregulating the progression and metastasis of NPC." (PMID 19949542, 2009). "Bulk RNA-seq data from PCa were analyzed to detect the mRNA levels of the model genes, revealing that, except for LTF and UBXN10, the other genes were highly expressed in tumor tissues." (PMID 40161494, 2025). "Among the pure bottleneck proteins, beta-COP, cAspAT, Gal-3, lactotransferrin, PDHE1-B, N-WASP, and WDR5 resulted in significantly varied tumor samples based on statistical comparisons." (PMID 39195201, 2024). "A down-regulation of lactotransferrin was found in CRC, contrary to our results, which suggested its tumor-suppressing action in CRC cells." (PMID 39195201, 2024). "The total protein levels of LTF, LCP1, AZU1, and ENO1 were all shown to be downregulated in tumor tissues." (PMID 37304069, 2023). "Through two independent validation cohorts, we finally identified five fecal tumor immune-related proteins (CAT, LTF, MMP9, RBP4, and SERPINA3) as well as a biomarker panel that had definite diagnostic value for CRC." (PMID 37313408, 2023). "Lactotransferrin (LTF) has been reported to be downregulated in NPC tissues and acts as a tumor suppressor by repressing the AKT signaling pathway in NPC." (PMID 33564686, 2021). "The expression level of LTF in 33 tumor types was negatively correlated with the TMB value of 17 tumor types (including PRAD) and the MSI value of 11 tumor types (including PRAD)." (PMID 34868909, 2021). "In 72 paired normal and tumor tissues from RCC patients, the LTF mRNA levels in most of the paired samples were downregulated in primary tumors." (PMID 32244557, 2020). "Four genes (EPB41L2, HLA-DQB1, LTF and SFRP1) were consistently overexpressed across multiple PFS cutoff times in initial tumor samples of patients with disease progression following topotecan treatment." (PMID 31195594, 2019).
tumor (continued). "The region located between 3p21.3 and 3p14.3, deleted in both cell sub-lines, contains several established tumor suppressor genes including LTF, TDGF1, WNT5a, and RASSF, as well as candidate tumor suppressors such as CACNA2D3, GNAI2, and SEMA3B." (PMID 23951555, 2013). "Cellular gene alterations also contribute to NPC development, especially inactivation of tumor suppressor genes, such as SPLUNC1, UBAP1, BRD7, NOR1, NGX6 and LTF, which are involved in different stages of NPC initiation and progression." (PMID 19949542, 2009). "Notably, like LTF, HNRNPF exhibited low expression levels in cancer, further highlighting a potential regulatory mechanism within the tumor context." (PMID 40082405, 2025). "They found that the absent expression or downregulation of LTF is widespread in these tumors and promotes tumor proliferation, while the overexpression of LTF inhibits the proliferation." (PMID 38763993, 2024). "Likewise, the expression levels of most of the genes were strongly related to the tumor grade in the CGGA and Gravendeel cohorts, except for the LTF expression between grades Ι and ΙΙ in the Gravendeel dataset (p = 0.056)." (PMID 37545464, 2024). "The outcomes indicated that there were LTF expression variations in subgroups of tumor stage and N and T stages, SFXN3 in subgroups of tumor stage and M, N, T stage, and TFR2 in subgroups of M, T stage and tumor stage." (PMID 37361050, 2023). "In addition, several of the proteins related to the regulation of iron metabolism, including lactoferrin (LTF), transferrin receptors 1/2 (TFR1, TFR2), transferrin (TF), and ceruloplasmin (CP), have been identified as tumor markers." (PMID 35028002, 2022). "The low expression of LTF is mainly concentrated in the promotion of biological pathways such as cytokine–cytokine receptor interaction, Janus kinase (JAK)/STAT signaling pathway, tumor pathway, and PRAD development pathway." (PMID 34868909, 2021). "An increase in serine proteases HTRA3, myeloblastin and lactotransferrin in all stages and metalloproteinases (MMP-9, ADAMTS4 and neutrophil elastase) in CC NM and CC M, supports degradation of the stroma surrounding the tissues as the tumor progresses." (PMID 31889941, 2019). "Identification of seven genes (MYLK, KLK2, KLK3, HAN11, LTF, CSRP1, TGM4) which have their connectivity altered between normal/tumoral conditions may provide novel insights into specific targets against tumor progression." (PMID 19055846, 2008). "Taken together, the LTF was overexpressed and may not act as a tumor suppressor in GBM, which was quite different from that in other tumors." (PMID 38763993, 2024). "Finally, we discovered that the 12 IMRGs expression had significant differences, among which SFXN3, TFR2, TMPRSS6, HMOX1, and LCN2 expressions were elevated in the cancer group, and SCARA5, LTF, STEAP2, SLC39A14, CP, ALAS2, and TF were low expressed in the tumor group." (PMID 37361050, 2023). "More importantly, we verified through cell experiments that LTF overexpression mediates JAK/STAT pathway to inhibit STAT3 expression and reduce tumor-derived GM-CSF secretion, regulate tumor immune microenvironment, and inhibit tumor cell proliferation and migration." (PMID 34868909, 2021). "The findings imply that LTF, AZU1, and ENO1 are related to tumor grade, while LCP1 is not substantially different among tumor stages." (PMID 37304069, 2023). "A number of interferon-stimulated genes (ISGs) were found to be highly induced in tumor compared to non-tumor samples, such as GBP1, CAMP, PTGS2, GOLIM4, IFIT3, MX1, LTF, and CYBB." (PMID 34400640, 2021). "Four genes (EPB41L2, HLA-DQB1, LTF and SFRP1) were consistently overexpressed in initial tumor samples of subsequent nonresponders across multiple PFS cutoff times." (PMID 31195594, 2019).
cancer (55 papers, 2010 to 2025). A tumor composed of atypical neoplastic, often pleomorphic cells that invade other tissues. "It has been shown that lactotransferrin, found in all body fluids, is an active agent against microbes and parasites and has been implicated in protection against cancer." (PMID 34358033, 2021). "In our previous report, we have demonstrated that a low-level LTF expression is associated with a high risk for cancer metastasis and poor prognosis in TCGA ccRCC patients." (PMID 34944711, 2021). "Further studies showed that LTF expression is significantly upregulated in cancer-associated adipose tissues from HGSC patients than in normal adipose tissues from healthy women using immunohistochemical analysis (n = 7 for each group, p = 0.001)." (PMID 32669559, 2020). "There are only a few studies investigating the link between LTF gene polymorphisms and cancer risk." (PMID 36360322, 2022). "Immune cell infiltration analysis presented that high LTF expression exhibited dysregulated immune infiltration (i.e., CD4 + T cells, neutrophils, macrophages, myeloid dendritic cells and cancer associated fibroblast)." (PMID 38763993, 2024). "At this point, after verifying the radioresistance ability of two radioresistant LUSC cell lines (H226R and H1703R), the RNA and proteomic analyses both revealed that LTF was the most significantly upregulated gene in radioresistant cancer cells." (PMID 37056929, 2023). "Lactotransferrin (LTF) is a protein that binds directly to NEDD4L, and NEDD4L-targeted degradation of LTF inhibits iron accumulation and subsequent iron-related death in various cancer cells." (PMID 38027016, 2023). "For instance, Lactotransferrin (LTF), a member of the transferrin family, not only regulates iron transport but also has roles in combating inflammation, microbial infection, cancer development, and metastasis." (PMID 38186569, 2023). "It has been suggested in some reports that the LTF can regulate cell growth, migration, and invasion in several cancers." (PMID 37056929, 2023). "LTF has also been studied as a nanoparticle carrier for a variety of preclinical cancer therapies, including in GBM, where it is able to penetrate the brain." (PMID 37252795, 2023). "Three genes, AMACR (ENSG00000242110), PCAT14 ((ENSG00000280623) prostate cancer-associated transcript 14), and LTF (lactotransferrin) are frequently compared in studies of prostate data." (PMID 36360315, 2022). "As LTF (ENSG00000012223) is downregulated in both sets, it is largely associated with cellular growth and differentiation regulation, cancer formation, and metastasis." (PMID 36360315, 2022). "At first, the anti-metastatic potential of omentin-1 tries to block the penetration of the cancer cells through mesothelium, probably by involving lactotransferrin (LTF)." (PMID 34588926, 2021). "The data showed that LTF mRNA is relatively lower in primary tumors from ccRCC patients with cancer metastasis." (PMID 32244557, 2020). "In the present study, the LTF mRNA level was low in primary tumors from ccRCC patients with cancer metastasis." (PMID 32244557, 2020). "The direct role of LTF-mediated ferroptosis in non-cancer cells and tissue injury remains to be further studied." (PMID 33117818, 2020). "LTF has a wide spectrum of properties that include anti-bacterial, anti-viral, and anti-cancer activities and is involved in the regulation of cellular growth." (PMID 30009039, 2018). "Immune‐related proteins–osteopontin (Spp1), lactotransferrin (Ltf), calreticulin (Calr) and peroxiredoxin 2 (Prdx2)–were associated with systemic myeloid‐derived suppressor cell (MDSC) burden, highlighting their potential roles in malignant tumors." (PMID 39939411, 2025). "Since ferroptosis is driven by iron-dependent lipid peroxidation, we hypothesized that AR could suppress this process by downregulating LTFe and its downstream target LTF, thereby promoting cancer cell survival." (PMID 40082405, 2025).